CTHRC1 (collagen triple helix repeat containing 1)
Diseases named in the same sentence as CTHRC1 in open-access papers (continued):
Sharing a sentence is not in itself a finding about the gene and the disease.
Hepatic steatosis (2 papers, 2014 to 2017). Steatosis is a term used to denote lipid accumulation within hepatocytes. "Recent studies also show that this factor has a metabolic function, as whole-body Cthrc1 deficiency will promote liver steatosis and increased subcutaneous fat mass." (PMID 28209124, 2017). "The development of hepatic steatosis in Cthrc1 null mice in the absence of any detectable Cthrc1 expression in the liver led to our discovery that Cthrc1 is a hormone with pituitary and remodeling bone as likely sources contributing to circulating levels." (PMID 24945147, 2014).
infarction (2 papers, 2022 to 2023). A localised pathological necrosis of tissue resulting from obstruction of the blood supply usually by a thrombus, an embolus, or vascular torsion. "A population of fibroblasts expressing high levels of Cthrc1 (the gene encoding collagen triple helix repeat containing 1, a secreted glycoprotein that promotes cell migration) emerged after infarction and was implicated in repair and protection from rupture." (PMID 35563692, 2022). "Therefore, this study aimed to explore the effect of CTHRC1 on post-infarction cardiac repair and its underlying molecular mechanisms." (PMID 36923925, 2023). "Using a permanent mouse model of acute MI, we further illuminated a protective role for cardiac fibroblast-derived CTHRC1 in post-infarction wound repair." (PMID 36923925, 2023). "Through direct effects on cardiac fibroblast migration and activation in the infarcted tissue, CTHRC1 enhances post-infarction wound repair and reduces cardiac rupture as well as the mortality rate via selectively activating non-canonical WNT5A-PCP signaling pathway." (PMID 36923925, 2023). "Importantly, rWNT5A protein treatment could reverse Cthrc1 deficiency-induced post-MI cardiac rupture, which further supports that CTHRC1 promoted post-infarction cardiac repair via selectively activating non-canonical WNT5A-PCP signaling pathway other than canonical WNT3A-β-catenin signaling axis." (PMID 36923925, 2023).
ischemic heart disease (2 papers, 2023 to 2026). "To further confirm the increased Cthrc1 expression in ischemic heart disease, we analyzed patients' data from GSE46224 dataset." (PMID 41362745, 2026). "The up-regulated molecule collagen triple helix repeat containing 1 (CTHRC1) attracted our attention owing to its high conservatism and association with vascular remolding, which is worthy of further investigation in ischemic heart disease." (PMID 36923925, 2023).
liver cirrhosis (2 papers, 2014 to 2017). "We further statistically analyzed CTHRC1 messenger RNA (mRNA) abundance with real-time RT-PCR in six relevant groups of samples: normal liver (NL), liver cirrhosis (LC), GI (Edmondson-Steiner grade I), GII, GIII, and GIV HCCs." (PMID 29285247, 2017). "Moreover, re-validation with qRT-PCR revealed that expression levels of CTHRC1 mRNA increased from normal tissues to liver cirrhosis and HCC in a stepwise manner." (PMID 24841500, 2014). "The gene that coded for collagen triple helix repeat containing 1 (CTHRC1), located at chromosome 8q22.3, was overexpressed in HCC compared with normal or liver cirrhosis tissues and identified as a new HCC-related gene." (PMID 24841500, 2014).
muscular dystrophies (2 papers, 2024 to 2025). "Apart from its documented involvement in cardiovascular disease, cancer, and RA, an expanding body of research also associates CTHRC1 with fibrotic conditions such as systemic lupus erythematosus, muscular dystrophies, and fibrosis in the lung, heart, liver, and skin." (PMID 38891078, 2024). "Similarly, in muscular dystrophies, CTHRC1-mediated alterations in fibroblast activity and extracellular matrix turnover exacerbate tissue fibrosis, leading to progressive muscle degeneration." (PMID 38891078, 2024). "Additionally, collagen triple helix repeat containing 1 (CTHRC1), one of the top 20 upregulated genes in WB and upregulated also in SM muscles, was previously reported in severely damaged skeletal and cardiac muscles of mice with muscular dystrophies." (PMID 40841884, 2025).
renal carcinoma (2 papers, 2021 to 2023). A carcinoma arising from the epithelium of the renal parenchyma or the renal pelvis. "It has been reported previously that the CTHRC1 correlates with kidney functions during renal cancer progression; our study revealed that CTHRC1 can be a sensitive, reliable, and more affordable marker for kidney functions." (PMID 37109608, 2023).
skin carcinoma (2 papers, 2014 to 2016). "In human colon, gastric, breast, endometrial, pancreatic, kidney, lung and skin cancer, Cthrc1 was expressed by activated stromal cells and not the cancer cells themselves." (PMID 24945147, 2014).
squamous cell carcinoma (2 papers, 2014 to 2017). A carcinoma arising from squamous epithelial cells. "In both the squamous cell carcinoma group and adenocarcinoma group, patients with high CTHRC1 expression showed a shorter survival time in comparison to those with low CTHRC1 expression (p<0.001)." (PMID 25238260, 2014). "Higher copy number of CTHRC1 was especially found in 13 non-keratinizing squamous cell carcinoma as compared with normal (n = 98), adeno-carcinoma (n = 1), keratinizing squamous cell carcinoma (n = 5) and squamous cell carcinoma (n = 83) in TCGA cervix." (PMID 28303973, 2017).
systemic lupus erythematosus (2 papers, 2021 to 2024). An autoimmune multi-organ disease typically associated with vasculopathy and autoantibody production. "In systemic lupus erythematosus, aberrant CTHRC1 expression has been linked to the dysregulation of immune responses and tissue remodeling, contributing to the development of fibrotic manifestations." (PMID 38891078, 2024). "Moreover, CTHRC1 was also identified as a novel serum biomarker associated with disease activity in systemic lupus erythematosus (SLE,)." (PMID 33670905, 2021). "In systemic lupus erythematosus, significant increases in CTHRC1 levels in the plasma and serum of patients have been observed." (PMID 38891078, 2024).
benign ovarian tumor (1 paper, 2015). "We used Western blots to examine CTHRC1 expression in tissue samples used for proteomic analysis (EOC tissues, n = 8 and benign ovarian tumor tissues, n = 8)." (PMID 26452130, 2015).
breast tumour (1 paper, 2022). "Mass spectrometric data from 125 breast tumour samples showed CTHRC1, POSTN and MMP13 to all be significantly higher in breast tumour tissue relative to normal while SFRP4 and FNDC1 levels were unaffected." (PMID 36190948, 2022).
cecum adenocarcinoma (1 paper, 2022). "According to TCGA data, CTHRC1 expression was 6.222-fold higher in colorectal adenocarcinoma, 10.224-fold higher in mucinous colon adenocarcinoma, 4.803-fold higher in rectal adenocarcinoma, and 4.643-fold higher in cecum adenocarcinoma compared with normal tissues." (PMID 35307012, 2022).
cervical tumor (1 paper, 2017). "In another TCGA dataset, the expression of CTHRC1 also increased in 3 cervical tumor tissues compared to the matched non-tumor tissues." (PMID 28303973, 2017).
chronic thromboembolic pulmonary hypertension (1 paper, 2025). Chronic thromboembolic pulmonary hypertension (CTEPH) is characterized by the persistence of thromboemboli in the form of organized tissue obstructing the pulmonary arteries. "Elevated plasma levels of CTHRC1 correlate with clinical indicators of right ventricular failure, and its levels decrease following successful balloon pulmonary angioplasty (BPA) in chronic thromboembolic pulmonary hypertension (CTEPH), suggesting its role in monitoring therapeutic efficacy." (PMID 41239459, 2025).
colorectal adenocarcinoma (1 paper, 2022). The most common type of colorectal carcinoma. "In addition, we assessed the association of CTHRC1 gene alterations with survival in patients with colorectal adenocarcinoma." (PMID 35307012, 2022). "In the current study, gene mutations in CTHRC1 accounted for 6% of colorectal adenocarcinomas." (PMID 35307012, 2022). "Gene alterations in CTHRC1 were found to occur in 6% of the 220 colorectal adenocarcinoma cases in the data obtained from the OncoPrint schematic of cBioPortal." (PMID 35307012, 2022).
endocervical carcinoma (1 paper, 2020). A carcinoma that arises from epithelial cells of the endocervix. "However, CTHRC1 was not correlated with B cells (r=−0.053, p=3.80e-01), CD4+ T cells (r=0.021, p=7.27e-01), CD8+ T cells (r=−0.063, p=2.98e-01), dendritic cells (r=0.041, p=4.98e-01), and neutrophils (r=−0.037, p=5.42e-01) in cervical and endocervical cancers." (PMID 33628726, 2020).
heart failure (1 paper, 2026). Inability of the heart to pump blood at an adequate rate to meet tissue metabolic requirements. "From the perspective of clinical translation, targeting Meox1/Cthrc1/p-Smad2/3 axis offers novel therapeutic potential for treating heart failure and improving the outcomes in patients with MI." (PMID 41362745, 2026). "From the clinical translational perspective, the present study suggests that Meox1/Cthrc1/p-Smad2/3 signaling pathway is a promising prognostic and therapeutic target for post-MI cardiac fibrosis and heart failure." (PMID 41362745, 2026). "Taken together, our results demonstrated that inhibiting Meox1/Cthrc1/p-Smad2/3 signaling suppressed CFs-to-Myofbs conversion and prevented fibrotic remodeling and heart failure, which may provide clinical translational implications for improving the prognosis of MI patients." (PMID 41362745, 2026).
hepatitis B virus infection (1 paper, 2021). A viral infection caused by the hepatitis B virus. "CTHRC1 expression is enriched in patients with hepatitis B virus infection and is highly correlated with the progression of HCC." (PMID 33505467, 2021).
Hypertension (1 paper, 2014). The presence of chronic increased pressure in the systemic arterial system. "Similarly, conditions evoking tissue remodeling, such as wound repair or angiotensin II-mediated hypertension, induced Cthrc1 expression in interstitial and adventitial fibroblasts and perivascular stromal cells." (PMID 24945147, 2014).
influenza (1 paper, 2025). An acute viral infection of the respiratory tract, occurring in isolated cases, in epidemics, or in pandemics; it is caused by serologically different strains of viruses (influenzaviruses) designated A, B, and C, has a 3-day incubation period, and usually lasts for 3 to 10 days. "Additionally, studies demonstrate that AMF-like cells in influenza-induced lung injury upregulate fibrotic markers such as Alpha smooth muscle actin (α-SMA/ACTA2) and Collagen triple helix repeat containing 1 (CTHRC1), further suggesting that their over-activation can lead to fibrosis development." (PMID 40607394, 2025).
intestinal tumors (1 paper, 2022). "In addition, CTHRC1 mRNA was significantly upregulated in all intestinal tumors." (PMID 35307012, 2022).
ischemic cardiomyopathy (1 paper, 2026). Ischemic cardiomyopathy is a cardiomyopathy in which a weakness in the muscle of the heart due to inadequate oxygen delivery to the myocardium with coronary artery disease being the most common cause. "The results showed that Cthrc1 was obviously upregulated in the hearts of patients with ischemic cardiomyopathy compared to non-failing hearts." (PMID 41362745, 2026).
malignant glioma (1 paper, 2022). A grade III or grade IV glioma arising from the central nervous system. "Of the 12 overexpressed genes, ABCC3, COL8A1, IBSP and PDPN are reportedly associated with GBM, while CTHRC1, PDLIM4 and MYL9 are associated with high-grade and malignant gliomas, respectively." (PMID 35456975, 2022).
metastatic cancers (1 paper, 2025). A carcinoma which has spread from the original site of growth to another anatomic site. "For example, we identified CTHRC1 as a key gene in driving metastatic progression, and it has been previously implicated in several metastatic cancers." (PMID 39748426, 2025).
metastatic tumor (1 paper, 2022). "Interestingly, we found that CTHRC1, NTM, PDGFC, PDLIM3, and SLC16A3 are gradually upregulated from normal to a metastatic tumor, indicating the association of these genes in tumor progression (Welch’s t-test, p < 0.05)." (PMID 35991839, 2022). "Moreover, the CTHRC1, PDGFC, PDLIM3, NTM, and SLC16A3 genes are gradually increased from normal tissue to the tumor and tumor to the metastatic tumor, and FBN2 showed the reverse pattern." (PMID 35991839, 2022).
mucinous adenocarcinoma (1 paper, 2022). An invasive adenocarcinoma composed of malignant glandular cells which contain intracytoplasmic mucin. "The gene mutation of CTHRC1 in COAD was 4.65%, and the change frequency of CTHRC1 in mucinous adenocarcinoma of the colon and rectum was the highest, up to 13.04%." (PMID 35307012, 2022).
osteosarcoma (1 paper, 2024). A usually aggressive malignant bone-forming mesenchymal neoplasm, predominantly affecting adolescents and young adults. "Collagen triple helix repeat containing 1 (CTHRC1) is a gene that has been repeatedly shown to be overexpressed in osteosarcoma and is not only involved in carcinogenesis but is also a prognostic marker for malignancy, progression, and OS survival." (PMID 38966281, 2024). "Downregulation of CTHRC1 would be an excellent target to stop the metastases of osteosarcoma." (PMID 38966281, 2024). "CTHRC1 is related to metastasis development and osteosarcoma invasion." (PMID 38966281, 2024). "Recent research has shown that CTHRC1 plays an important role in osteosarcoma progression." (PMID 38966281, 2024).
ovarian serous cystadenocarcinoma (1 paper, 2021). A malignant serous cystic epithelial neoplasm arising from the ovary. "The highest frequency CTHRC1 alteration (> 12%) was observed in patients with ovarian serous cystadenocarcinoma, with “amplification” as the primary type." (PMID 34702252, 2021).
papillary thyroid carcinoma (1 paper, 2024). "Recent studies have also reported that CTHRC1 is associated with the onset and malignant transformation of papillary thyroid carcinoma." (PMID 39052013, 2024). "In papillary thyroid carcinoma, CTHRC1 was demonstrated to be correlated with tumor occurrence and malignant transformation, and it may play a crucial role in regulating EMT." (PMID 39052013, 2024). "Furthermore, CTHRC1 has been shown to promote cell proliferation and inhibit apoptosis by activating the ERK1/2 signaling pathway in papillary thyroid carcinoma." (PMID 39052013, 2024).
peripheral nerve injury (1 paper, 2019). Injury to a peripheral nerve. "LncRNA NONMMUG014387 was upregulated after peripheral nerve injury and could promote SC proliferation by increasing collagen triple helix repeat containing 1 (Cthrc1) and activating Wnt/PCP pathway." (PMID 31316349, 2019).
peripheral nerve tumors (1 paper, 2025). "We assessed POSTN and CTHRC1 expression in human patient-derived MPNST samples and a tissue microarray (TMA) composed of core biopsies from benign and malignant human peripheral nerve tumors." (PMID 39511408, 2025).
postmenopausal osteoporosis (1 paper, 2008). Metabolic disorder associated with fractures of the femoral neck, vertebrae, and distal forearm. "In view of an anabolic effect of Cthrc1 on bone formation, we tested whether Cthrc1 may impact bone mass in the OVX mice, an established preclinical disease model of postmenopausal osteoporosis." (PMID 18779865, 2008).
renal fibrosis (1 paper, 2023). A final common manifestation of a wide variety of chronic kidney diseases characterized by glomerulosclerosis and tubulointerstitial fibrosis. "At the current level of understanding, CTHRC1 might have a role in renal fibrosis, as it inhibits the TGFβ/Smad pathway." (PMID 37109608, 2023).
rhabdomyosarcoma (1 paper, 2021). A rare aggressive malignant mesenchymal neoplasm arising from skeletal muscle. "Additionally, the CTHRC1 protein was localized in the nucleus of RH-30 (metastatic rhabdomyosarcoma cell line) cells and secreted extracellularly." (PMID 34702252, 2021).
Stroke (1 paper, 2012). Sudden impairment of blood flow to a part of the brain due to occlusion or rupture of an artery to the brain. "However, one third of the genes were increased with suboptimal timing in aged rats, either on day 3 post-stroke (Adam17, Gpc3, Mmp14, Nid2, Tagln, Wnt5b) or on day 14 after stroke (Col4a2, Col8a1, Cthrc1, Cxcl1, Gpc3, Tgfbr2)." (PMID 23251410, 2012).
tendinopathy (1 paper, 2024). "The present study aims to investigate the function and underlying mechanism of CTHRC1 in tendinopathy." (PMID 39540237, 2024). "Second, this study doesn't employ conditional CTHRC1 KO mice to more convincingly investigate the specific effect of CTHRC1 in tendinopathy." (PMID 39540237, 2024). "We demonstrated that CTHRC1 could promote tendon healing and attenuate tendinopathy by enhancing the proliferation, migration, and tenogenic differentiation of TSPC post‐injury." (PMID 39540237, 2024). "Our findings suggest that CTHRC1 offers a novel promising therapeutic strategy for tendinopathy." (PMID 39540237, 2024). "In contrast, CTHRC1 deletion exacerbated tendinopathy in vivo." (PMID 39540237, 2024). "CTHRC1 holds promise as a potential intervention for tendinopathy." (PMID 39540237, 2024). "Our study highlights the positive role of CTHRC1 in tendon regeneration and suggests that CTHRC1 may be a promising new option for tendinopathy treatment." (PMID 39540237, 2024). "Consequently, we believe that supplementation of CTHRC1, with the aim to maintain its consistently high levels during tendon healing, holds promise as a potential therapeutic approach for tendinopathy." (PMID 39540237, 2024). "Specifically, CTHRC1 interacts with EGFR and subsequently activates the MAPK signaling pathway to promote TSPC proliferation, migration, and tenogenic differentiation, thus promoting tendon regeneration and attenuating tendinopathy." (PMID 39540237, 2024).
testicular germ cell tumor (1 paper, 2014). A germ cell tumor arising from the testis. "In a spontaneously occurring testicular germ cell tumor, Cthrc1 was detected in outer mural cells of remodeling small vessels." (PMID 24945147, 2014).
triple-negative breast carcinoma (1 paper, 2025). An invasive breast carcinoma which is negative for expression of estrogen receptor (ER), progesterone receptor (PR), and human epidermal growth factor receptor 2 (HER2). "Leveraging single-cell data from triple-negative breast cancer, we comprehensively explore the role of CTHRC1 within the tumor microenvironment, with a specific focus on immunoregulation and intercellular interactions." (PMID 40134434, 2025). "Investigating the pivotal role of CTHRC1 in the tumor microenvironment of triple-negative breast cancer (TNBC)." (PMID 40134434, 2025).
type 2 diabetes (1 paper, 2021). "While the percentage of CTHRC1 detectability in plasma is similar in our and Duarte study, there is a discrepancy in its regulation in type 2 diabetes." (PMID 34880217, 2021).